ERBB2 (erb-b2 receptor tyrosine kinase 2)
Diseases named in the same sentence as ERBB2 in open-access papers (continued):
Sharing a sentence is not in itself a finding about the gene and the disease.
breast cancer (continued). "Breast cancer cells, after MYC/KRAS- or MYC/ERBB2- ablation, are similar to glioma cells in their acquired resistance to phosphoinositol-3-kinase (PIK3) inhibitors." (PMID 32300553, 2020). "Previously, we reported that phytoestrogen/genistein exposure promoted ER-ErbB2/RTK crosstalk, which mediated genistein-induced ER+/ErbB2-overexpressing breast cancer cell growth." (PMID 31059536, 2019). "Therefore, the combination of anti-ErbB2 drugs with NF-kB inhibitors or proteasome inhibitors - which prevent NF-kB activation through inhibition of IkB degradation - may represent a novel and more valuable therapeutic approach to treat RANK-expressing ErbB2-positive breast cancers." (PMID 30621730, 2019). "On the other hand, knockdown of GRB7 expression has been indicated to attenuate ERBB2 and AKT phosphorylation in breast cancer cells, affecting ERBB2-mediated cancer growth in vivo." (PMID 31083325, 2019). "Co-expression of BCAR4 and low level of ERBB2 occurs frequently and indicate a worse PFS outcome for breast cancer patients undergoing tamoxifen resistance." (PMID 31762809, 2019). "ERBB2 (Erb-B2 Receptor Tyrosine Kinase 2, also known as HER2) is one of the most studied oncogenes, being considered a breast cancer biomarker (at the gene and protein levels), commonly overexpressed in HBC." (PMID 31301170, 2019). "The basal-like breast tumor subtype largely overlaps the triple negative type of breast cancer, which lacks or shows a low level of ESR1 and PGR expressions, and lacks ERBB2 amplification." (PMID 30621577, 2019). "ERBB2 has been identified as a client protein of HSP90 machinery and in lapatinib-resistant ERBB2-positive breast cancer cells HSF1-mediated heat shock pathway is responsible for the adaptation of the receptor tyrosine kinase kinome of cancer cells." (PMID 35582577, 2019). "Of note, TPBCs showed significantly lower rates of ERBB2 and MYC amplification than ER-PR-HER2+ breast cancers (ERBB2: 53% vs. 85%, P = 0.001; MYC: 24% vs. 47%, P = 0.013)." (PMID 31410192, 2019). "More recently, we discovered that disruption of the EGFR/ErbB2-dependent signalling by lapatinib and CP-724714, two inhibitors of the receptor tyrosine kinase (RTK), diminished the amplitude of the SOCE in breast cancer cells." (PMID 30917547, 2019). "ErbB2 (or HER2) is a member of the ErbB receptor tyrosine kinase family; its overexpression is observed in approximately 20% of human breast cancers and correlates with poor prognosis." (PMID 30621730, 2019). "For example, a member of the ERBB family ERBB2, also known as HER2, is amplified in about 30% of all breast cancers and overexpression of EGFR (epidermal growth factor receptor) is found in more than 50% of non-small cell lung cancer." (PMID 31333463, 2019). "Another study on BCL9 in breast ductal carcinoma confirmed that its methylation status and expression pattern are definitely functionally related to the expression of ERBB2 and HER2 in breast cancers." (PMID 31480430, 2019). "HER2 (or ErbB2), one of the epidermal growth factor receptors family (EGFR), is well-known to be overexpressed in aggressive human breast cancer." (PMID 30832287, 2019). "In another previous study, we identified the same upstream effectors (ERBB2, RABL6, FOXM1 and MITF) to be the most effected by palbociclib treatment in the MDA-MB-231 breast cancer cells, reducing colony formation, cell migration and viability." (PMID 31835892, 2019). "In doing this, breast cancer cells overexpressing ErbB2 (SKBR3, AU565, and HCC1954) were treated with lovastatin, the FDA-approved tyrosine kinase inhibitors against ErbB2 (lapatinib and neratinib), or the combinations as indicated." (PMID 30786890, 2019). "Our study focused on assessment of ERBB2 (HER2) amplification in patients with solid tumors, excluding breast cancer, who underwent next-generation sequencing." (PMID 32923865, 2019).
breast cancer (continued). "The receptor tyrosine protein kinase ERBB2 is the protein product of the HER-2/NEU gene and is routinely being used for breast cancer classification into HER2+ or HER2− phenotypes." (PMID 31315058, 2019). "In all analyses conducted in breast cancer cells, we found an excellent correlation between ERBB2 transcript abundance and HER2 protein levels corresponding to the previously published data." (PMID 31430289, 2019). "It has been well elucidated that ErbB2 and ErbB4 activation initiates PI3K signaling cascades in different tissues such as skeletal muscle and breast cancer cells." (PMID 30971932, 2019). "In this paper we tried to elucidate the mechanism by which ERBB2/STARD10 crosstalk promotes ethanol induced cell growth and migration in breast cancer cells." (PMID 30611309, 2019). "None of the samples showed a positive finding on OncoScan, despite the high prevalence of SCNAs in breast cancers, often involving deletion of PIK3CA or amplification of ERBB2." (PMID 30858924, 2019). "Thus, it could become a drug for the treatment of ErbB2+ breast cancer." (PMID 31408580, 2019). "Lapatinib is a clinically approved drug which targets ERBB2 and EGFR in the treatment of breast cancer." (PMID 31645597, 2019). "Many clinically important genes in breast cancer, e.g. ESR1 and ERBB2, appear to follow a bimodal expression distribution across the samples of a cohort." (PMID 31072345, 2019). "In breast cancer, MBP-1 expression inversely correlates with the ErbB2 and Ki67 expression levels and it is a good predictor of disease-free survival." (PMID 31416219, 2019). "In contrast, in the fourth patient, who suffered from bilateral breast cancer, the samples (p-5 and p-33) show a difference in CNV and the ERBB2 AS, reaffirming the diagnosis of two independent tumors." (PMID 31827209, 2019). "In breast cancer xenografts, overexpressing EIF4E induces resistance to ERBB2 and EGFR inhibitors including lapatinib." (PMID 30072418, 2019). "The vast majority of luminal A and B tumors express the estrogen receptor; in contrast, most basal breast cancers are triple negative breast cancers (TNBC) that lack expression of the estrogen, progesterone and ERBB2 (HER2) receptors." (PMID 30754719, 2019). "Since its identification in 1985, the human ERBB2 (HER2) oncogene has ranked highest with regard to its relevance in oncology, especially breast cancer (BC)." (PMID 31261614, 2019). "No clinically accepted biomarkers are as yet available for estimation of response to human epidermal growth factor receptor 2 (currently known as ERBB2, but referred to as HER2 in this study)–targeted therapy in breast cancer." (PMID 31002322, 2019). "Since our preliminary data proves that ethanol treatment causes STARD10 and ERBB2 upregulation in vivo and in vitro, we further explored the role of STARD10 in ethanol-induced tumor promotion to test the hypothesis that STARD10 and ERBB2 cooperate in ethanol induced breast cancer." (PMID 30611309, 2019). "HER-2, a member of the EGF receptor family of receptor tyrosine kinases (Erb), commonly referred as ErbB2, represents a prognostic biomarker in breast cancer and has been a molecular target for many years." (PMID 31488078, 2019). "ERBB2 (HER2) is a receptor tyrosine kinase (RTK) and potent oncogene that is amplified in ~ 20% of breast cancer cases." (PMID 30898150, 2019). "Breast cancer cell lines included MCF-7 MCF7-RAS, MCF7-Adriamycin resistant (ADR); normal immortalized breast cell lines included MCF10A, MCF10A-Neo, MCF10A-RAS/ErbB2 and MCF10A-TGFα." (PMID 29928491, 2018). "It was recently reported that the combined inhibition of EGFR/ErbB2 (via lapatinib) and c-ABL (via imatinib) in fulvestrant-resistant breast cancer cells significantly inhibited cell growth and autophagy." (PMID 30214383, 2018).
breast cancer (continued). "We observed that lapatinib, a small-molecule ErbB2/EGFR inhibitor used for treatment of ErbB2-positive breast cancer, strongly upregulates Irf6 in detached ErbB2-positive human breast cancer cells BT-474, AU-565, and HCC-1419." (PMID 30545388, 2018). "When analyzing different breast cancer molecular subtypes (normal-like, luminal A, luminal B, ERBB2 (Erb-B2 Receptor Tyrosine Kinase 2), and basal), ERBB2 and basal tumors show significantly lower FBXW7 expression compared to normal-like tumors." (PMID 30086763, 2018). "In breast cancer, copy number amplification is a well-known mechanism of ERBB2 overexpression, and treatment of these HER2+ patients with trastuzumab is an established and effective targeted therapy." (PMID 29617662, 2018). "Of the patients with HER2-positive breast cancer in cluster C1, 75% showed activation of the RTK pathway that includes the HER2 (ERBB2) protein." (PMID 30297783, 2018). "In our study, we examined the anti-cancer effects of ganetespib on ErbB2+ BT474 and SKBR3 breast cancer cells, and isogenic paired cancer cell lines with lentivirus-mediated ErbB2 overexpression." (PMID 29717218, 2018). "The HER2 protein, also called ERBB2, is commonly overexpressed in patients with breast cancer, which accounts for approximately 15–30% cases in breast cancer." (PMID 29473044, 2018). "In breast cancer cells, copine-III binds to the tyrosine kinase receptor ErbB2 (HER2) in a phosphorylation-dependent manner to activate Src for cancer cell migration." (PMID 29867202, 2018). "As such, the dose-dependent decrease in total ErbB2, Akt, Src, and GSK3 expression after ganetespib treatment in the ErbB2+ breast cancer cells is indicative of potential protein degradation." (PMID 29717218, 2018). "We also added genes important for breast cancer biology or subtyping (ER, PGR, ERBB2, MKI67, AURKA and FOXC1)." (PMID 29973242, 2018). "To gauge the confounding nature of commonly amplified genes in breast cancer, we further performed multivariate analysis on the candidate genes with cases of amplification of MYC, FGFR1, CCND1, and ERBB2." (PMID 30181556, 2018). "In the context of breast cancer, ERBB2 (HER2) is clearly the most widely studied TAA among these four candidate immunogens." (PMID 29867922, 2018). "Compensatory activation of ErbB2 and downstream MAPK and Akt signaling in AI-resistant ER+ breast cancer cells resulted in the upregulation of miR-21 and downregulation of its target PDCD4." (PMID 30214383, 2018). "MS275 induces apoptosis of erbB2-overexpressing cells, sensitizes TRAIL-resistant breast cancer cells, inhibits angiogenesis and metastasis, as well as reverses EMT." (PMID 30547810, 2018). "Our experiments showed that ganetespib potently inhibits ErbB2+ BT474 and SKBR3 breast cancer cells, as indicated by MTT and clonogenic assays." (PMID 29717218, 2018). "In regards to the clinical significance of HSP90 in ErbB2-mediated breast cancer, targeting HSP90 is emerging as a novel therapeutic strategy to destabilize and degrade its client proteins, particularly ErbB2." (PMID 29717218, 2018). "While quercetin decreased ErbB2 tyrosine kinase activity and the phosphorylation of PI3K and AKT om SKBR3 breast cancer cells, it reduced the phosphorylation of ERK1/2 and AKT phosphorylation and inhibited the NF-κB pathway in HepG2 liver cancer cells." (PMID 30597838, 2018). "Within this profile, luminal breast cancers respond to estrogen receptor targeted therapy, HER2+ tumors to Herceptin and other ErbB2-blocking agents, and basal tumors to chemotherapy only." (PMID 30550540, 2018). "Two studies categorized patients into hormone receptor-positive, ERBB2-positive, and triple-negative breast cancer (TNBC) patients according to the clinicopathological features of breast cancer." (PMID 29416807, 2018).
breast cancer (continued). "Different subtypes of breast cancers have different preferred clinical therapeutic strategies, such as anti-Estrogen therapy for Luminal A/B type, ERBB2 (Her2) target therapy for Her2/Luminal B type and chemotherapy for Basal type." (PMID 29507663, 2018). "Breast cancer is classified into different molecular sub-types based on receptor expression which are luminal-A, luminal-B, HER’s-2-enriched (ERBB2+), triple negative breast cancers (TNBCs) and normal-like breast cancers." (PMID 30335837, 2018). "ANT2 knockdown with shRNA was previously found to inhibit receptor tyrosine kinase ErbB2 and PI3K in breast cancer cells." (PMID 29484131, 2018). "ERW decreased ErbB2/neu expression and impaired pERK1/ERK2 and AKT phosphorylation in breast cancer cells." (PMID 30402124, 2018). "ErbB2 (also called HER2) is tyrosine kinase receptor, member of the human epidermal growth factor receptor family, and is overexpressed in 25–30% of breast cancers." (PMID 29467663, 2018). "Based on these thresholds, the assay can be used for the robust quantification of ERBB2, ESR1, PGR and MKI67 on whole sections of FFPE samples during routine histopathological work-up of breast carcinoma." (PMID 30342538, 2018). "This is clinically meaningful since ERBB2 gene amplification remains, to date, the sole approved CNA biomarker in breast cancer." (PMID 28685159, 2017). "We found that buformin reduced cell viability in erbB-2-overexpressing SKBR3 (IC50 = 246.7 μM) and BT474 (IC50 = 98.6 μM) breast cancer cell lines." (PMID 28193239, 2017). "In the MMTV-NEU-NT transgenic mice used in the present study, tumours arise spontaneously in the mammary tissue by overexpression of the activated form of the NEU/HER2 oncogene, similar to the ERBB2 gene that is amplified in many human breast cancers." (PMID 28261475, 2017). "In contrast, luminal cancers express breast cancer differentiation markers (KRT20, CD24, ERBB2, and GATA3) and uroplakins which are markers of terminal urothelial differentiation." (PMID 28102366, 2017). "As a preliminary experiment for in vivo studies, we tested the effects of lapatinib on cell proliferation in erbB-2-overexpressing 78617 and 85815 cells, which were derived from MMTV-erbB-2 transgenic mouse mammary tumors." (PMID 28061785, 2017). "HER2, also termed ERBB2 or EGFR2, is overexpressed in more than 30% of breast cancers and has been shown to play an important role in the progression of certain aggressive breast cancers." (PMID 29112149, 2017). "One of the ongoing challenges in the treatment of breast cancer is the emergence of acquired resistance to therapies targeting oncogenic drivers such as PI3K and ErbB2." (PMID 28783168, 2017). "The human epidermal growth factor receptors ErbB2, HER2, and HER3 and carbohydrate antigen 15-3 (CA 15-3) are biomarkers of breast cancer." (PMID 28825646, 2017). "Doxorubicin and the ERBB2 targeted therapy, trastuzumab, are routinely used in the treatment of HER2+ breast cancer." (PMID 29367538, 2017). "In the human breast cancer cell line SKBR3, tyrosin kinase receptors ERBB2 and ERBB3 are downregulated by miR-125a leading to diminished cell proliferation and migration." (PMID 28445974, 2017). "We evaluated the expression of ERRF in breast cancer in publically available databases, and correlated ERRF expression to responses to both ERBB2-targeted therapies and patient survival." (PMID 28415602, 2017). "We selected ERBB2, GRB7 and ONECUT2 for validation due to their importance in the biology of breast cancer, the magnitude of the change found in the RNA-seq data analysis and the consistency between the European and IA ancestry analyses." (PMID 28832682, 2017). "Despite the remarkable success of anti-HER2/ERBB2 therapies, patients with advanced HER2-positive breast cancer frequently display primary resistance." (PMID 29212182, 2017). "The nine-gene set is regulated by estrogen, ERBB2 and EGF signaling, all established breast cancer factors." (PMID 28411283, 2017).
breast cancer (continued). "The effect of copy number gains of known oncogenes such as ERBB2, CCND1 and C-MYC in breast cancer, was used to assess the robustness of the platform." (PMID 28697743, 2017). "Although MCF7 cell line is derived from ER-positive human breast cancer, MCF7 cells show detectable levels of ErbB2." (PMID 27791982, 2017). "The majority of breast cancers express estrogen, progesterone receptors (ER,PR), HER2 and/or ErbB-2." (PMID 29104587, 2017). "The expression of miR-125b is downregulated in various human cancers including glioblastoma, prostate cancer, ovarian cancer, and breast cancer by suppressing oncogenes such as EST1, ERBB2, ERBB3, and BAK1 as its targets." (PMID 28435518, 2017). "Breast cancer can be classified depending on the status of estrogen receptor (ER) and/or progesterone receptor (PGR) and epidermal growth factor receptor 2 (ERBB2/HER2) in clinic." (PMID 28392805, 2017). "Another two cell lines, BT-474 human breast cancer and YCU-H891 human head and neck squamous carcinoma cell lines, overexpressing ErbB2 were treated with EGCG to examine the inhibition of cell growth." (PMID 28286519, 2017). "In this study, we have paid attention to three different GFRs that are highly expressed on breast cancer, namely epidermal growth factor receptors (EGFR1 and ERBB2) and insulin-like growth factor 1 receptor (IGF1R)." (PMID 29119846, 2017). "We identified a high correlation between IHC for ERBB2 and MIP amplification of FFPE breast cancer specimen’s 17q13 loci, with 83% concordance between the two platforms." (PMID 28697743, 2017). "Co-amplification of ERBB2 and TOP2A has been reported in breast cancer cases, which has been attributed to their proximity to chromosome 17 (17q12 and 17q21.3-22, respectively)." (PMID 28915696, 2017). "This study also aimed to characterize ErbB signaling events involved in early breast cancer development by comparative phosphoproteomic analysis of HMLECs triggered with EGFR and ErbB3-specific ligands in the context of ErbB2 overexpression." (PMID 28174229, 2017). "Pathological biomarkers such as estrogen receptor (ER), progesterone receptor (PgR), ErbB2, Ki‐67, cytokeratins, and epidermal growth factor (EGF) receptor are mainly used in clinical situations to define breast cancer subtypes." (PMID 28781955, 2017). "For muscle-invasive disease, the direct comparison of the breast cancer subtypes and bladder cancer subtypes has been shown and the four targeted genes ESR1, PGR, ERBB2 and MKI67 have been shown to be of diverse expression in bladder cancer." (PMID 28978063, 2017). "IHC staining confirmed that ErbB2 was similarly expressed in lung metastatic lesions formed by LPP proficient and LPP knockdown breast cancer cells." (PMID 28436416, 2017). "The regulation of these pathways is critical in erbB-2-overexpressing breast cancers due to IGF1R and/or erbB-2 crosstalk with ER." (PMID 28193239, 2017). "Mediator of ErbB2-driven cell motility, Memo (gene name MEMO1), is a small ubiquitous redox-active protein with an important role in breast cancer cell migration, invasion, and metastasis downstream of growth factor signaling." (PMID 27472465, 2016). "The same results were obtained by performing experiments in ErbB2 positive breast cancer cell line SKBR3, further supporting the expression correlation between ErbB2 and p130Cas." (PMID 26716506, 2016). "Overexpression of human epidermal growth factor receptor 2 (HER2, also known as Neu, ErbB2, EGFR2) is found in approximately 20-25% of breast cancer patients." (PMID 27694691, 2016). "In breast cancer cell lines that overexpress ERBB2, increased levels of ERBB3 drive continued oncogenic signaling and, therefore, resistance to the ERBB2 inhibitory activity of the kinase inhibitors gefitinib and erlotinib." (PMID 26745281, 2016).